NRBP1 (nuclear receptor binding protein 1)
Diseases named in the same sentence as NRBP1 in open-access papers (continued):
Sharing a sentence is not in itself a finding about the gene and the disease.
gastric cancer (1 paper, 2025). A primary or metastatic malignant neoplasm involving the stomach. "We are the first to demonstrate that TRIM24 promotes gastric cancer progression through the degradation of NRBP1, a tumor suppressor protein." (PMID 41430038, 2025). "Additionally, TRIM24 can promote NRBP1 ubiquitination at the K430 residue, subsequently leading to its degradation, ultimately inhibiting apoptosis in gastric cancer cells." (PMID 41430038, 2025). "This discovery provides new mechanistic insights into how TRIM24 exerts its oncogenic effects and suggests that targeting TRIM24 or enhancing NRBP1 expression could serve as promising therapeutic strategies for the treatment of gastric cancer." (PMID 41430038, 2025).
glioma (1 paper, 2024). A benign or malignant brain and spinal cord tumor that arises from glial cells (astrocytes, oligodendrocytes, ependymal cells). "Only 21 out of 111 (18.9%) of the low‐grade glioma showed high expression of NRBP1, whereas 125 out of 194 (64.4%) of the high‐grade glioma showed high expression of NRBP1." (PMID 39149873, 2024). "The correlation between NRBP1 and glioma grade, prognosis in TCGA/CGGA databases and our clinical data were analyzed." (PMID 39149873, 2024). "To explore the NRBP1 function in gliomas, we compared NRBP1 mRNA expression in gliomas and normal tissues using the TCGA/GEPIA and CGGA datasets." (PMID 39149873, 2024). "Based on our analysis of clinical cases and bioinformatics data, our findings suggest a correlation between elevated NRBP1 expression and a higher glioma grade." (PMID 39149873, 2024). "Here, we present findings showcasing significantly elevated NRBP1 mRNA levels in GBM tissues when compared to both low‐grade glioma and normal tissues, thereby indicating a more unfavorable prognosis." (PMID 39149873, 2024). "Immunohistochemistry identified significantly higher positive staining intensity of NRBP1 in GBM tissues than in normal or low‐grade glioma tissues." (PMID 39149873, 2024). "In this context, we present preliminary findings regarding the expression of NRBP1 in clinical samples of glioma tissues as well as cultured GBM cell lines and transplanted tumor in nude mice." (PMID 39149873, 2024). "There was a correlation between elevated NRBP1 expression and advanced stage glioma, as well as decreased overall and disease‐free survival." (PMID 39149873, 2024). "Significantly upregulated mRNA expression of NRBP1 was observed in GBM tissues compared with that in normal or low‐grade glioma tissues." (PMID 39149873, 2024). "Nevertheless, the functional implications and expression patterns of NRBP1 in gliomas remain enigmatic." (PMID 39149873, 2024). "There was a greater expression of NRBP1 mRNA and protein in high‐grade glioma tissues compared to normal or low‐grade glioma tissues." (PMID 39149873, 2024). "Glioma cells showed significantly higher NRBP1 expression than HA1800 cells." (PMID 39149873, 2024). "The findings implied that an elevated NRBP1 expression is indicative of unfavorable survival rates in GBM and contributes to the development of glioma tumors." (PMID 39149873, 2024).
head and neck cancer (1 paper, 2015). A primary or metastatic malignant neoplasm affecting the head and neck. "This study identifies NRBP1 mutant to play an oncogenic role in head and neck cancer." (PMID 26572163, 2015). "As a proof of principle, integrated analysis of copy number variation, exome and transcriptome of 4 head and neck cancer cell lines and TCGA HNSCC dataset identify NRBP1, UBR5, ZNF384 and TERT as novel candidate oncogenes in HNSCC." (PMID 26572163, 2015).
Hypertension (1 paper, 2024). The presence of chronic increased pressure in the systemic arterial system. "The risk of hypertension is related to the NRBP1, REG4, CCNE2, and KCNJ11 genes." (PMID 38915894, 2024).
intestinal cancer (1 paper, 2025). "On the other hand, the tumor suppressor function of NRBP1 was first highlighted in hematological and intestinal cancers by gene knock-out studies in mice." (PMID 41430038, 2025).
lung adenocarcinoma (1 paper, 2025). A carcinoma that arises from the lung and is characterized by the presence of malignant glandular epithelial cells. "Likewise, NRBP1 upregulation is also correlated with good prognosis in lung adenocarcinoma." (PMID 41430038, 2025).
lymph node metastasis (1 paper, 2019). "Multivariate Cox proportional regression analysis revealed that NRBP1 expression (P = 0.014), age (P = 0.021), tumor grade (P = 0.011), and lymph node metastasis (P = 0.006) are independent prognostic factors for the overall survival of BCa patients." (PMID 31413746, 2019). "In the univariate analysis, NRBP1 expression (P < 0.001), tumor grade (P < 0.001), tumor stage (P < 0.001), and lymph node metastasis (P < 0.001) were the statistically significant predictors for overall survival." (PMID 31413746, 2019). "A significant positive correlation between increased NRBP1 expression and tumor stage, and lymph node metastasis was observed in 56 patients." (PMID 31413746, 2019).
oligodendroglioma (1 paper, 2024). A well-differentiated (WHO grade II), diffusely infiltrating neuroglial tumor, typically located in the cerebral hemispheres. "The negative correlation between NRBP1 and 1p/19q co‐deletion may be due to the requirement for IDH mutation in the diagnosis of oligodendroglioma, and 1p/19q co‐deletion is also one of the diagnostic criteria for oligodendroglioma." (PMID 39149873, 2024).
oral carcinoma (1 paper, 2015). "Knockdown of NRBP1 in an oral carcinoma cell line bearing NRBP1 mutation inhibit transformation and survival of the cells." (PMID 26572163, 2015).
tumor (14 papers, 2015 to 2025). "In addition, NRBP1 knockdown was associated with reduced Ki67 staining of tumour sections, indicating that this leads to lower MDA-MB-231_HM cell proliferation in vivo." (PMID 36693952, 2023). "A genetic analysis in Caenorhabditis elegans as well as in mice, suggested that NRBP1 influenced proliferation and homeostasis of intestinal progenitor cells and tumor formation." (PMID 40668933, 2025). "Human NRBP1(535 amino acids) has been shown to play dual roles in cancer progression, either suppressing or promoting tumor development." (PMID 41430038, 2025). "In these contexts, NRBP1 exhibits either oncogenic or tumor-suppressive properties to influence tumorigenesis and development." (PMID 40645931, 2025). "The tumor growth in the U87‐sh‐NRBP1 group was slower than that of the U87‐sh‐control group, and faster in the U251‐pcDNA‐NRBP1 group than the U251‐Control group." (PMID 39149873, 2024). "The U87‐sh‐NRBP1 group exhibited reduced average tumor volume and weight when compared to the U87‐sh‐control group." (PMID 39149873, 2024). "The suppression of proliferation, invasion, and migration of tumor cells was observed upon NRBP1 knockout, and in vitro studies also demonstrated the induction of apoptotic cell death." (PMID 39149873, 2024). "As an example, NRBP1 demonstrated anti‐tumor properties in intestinal cells, as evidenced by the heightened susceptibility of NRBP1‐null mice to intestinal malignancies." (PMID 39149873, 2024). "The recruitment of multiple proteins by NRBP1 and its regulation of varied downstream pathways provides a likely explanation for the contrasting and context-specific effects of NRBP1 on tumour progression." (PMID 36693952, 2023). "A tumour suppressor role for NRBP1 was first highlighted by a genetic screen in C. elegans and gene knock-out studies in mice, with the latter reporting haematological and intestinal tumours." (PMID 36693952, 2023). "The results indicated that compared to vector control, NRBP1 knockdown by either shRNA significantly reduced tumour metastasis to lung." (PMID 36693952, 2023). "NRBP2 shows a 59% amino acid similarity to NRBP1 which has been identified to regulate intestinal progenitor cell homeostasis and suppress tumor formation." (PMID 35491849, 2022). "NRBP2 has a 59% amino acid sequence similarity to nuclear receptor binding protein 1 (NRBP1) a pseudokinase identified as a tumor suppressor and needed for terminal differentiation of intestinal progenitor cells." (PMID 32517178, 2020). "Nrbp1 is considered to be an intestinal tumor suppressor gene as per the intestinal tumorigenic phenotype of the Nrbp1 conditional knockout mice." (PMID 31413746, 2019). "Taken together, these data suggest that NRBP1 possesses growth inhibitory and apoptosis enhancing activities and indeed acts as a tumour suppressor." (PMID 29567997, 2018). "Early tumour/node/metastasis (TNM) stage (stage I + II) was frequently identified with high NRBP1 expression (P = 0.012)." (PMID 29567997, 2018). "A xenograft mouse model was established to investigate the influence of NRBP1 on tumour growth in vivo." (PMID 29567997, 2018). "Tumours grew faster in the control group, and the mean volume of tumours derived from the cells transduced with lenti-NRBP1 was significantly smaller than those derived from cells transduced with lenti-GFP during the entire period." (PMID 29567997, 2018). "In terms of OS, univariate analysis revealed that tumour NRBP1 expression status, gender, differentiation grade, pT stage, pN stage, pM stage and TNM stage were prognostic factors." (PMID 29567997, 2018). "The results of the multivariate analysis showed that tumour NRBP1 expression status, gender, differentiation grade, pM stage and TNM stage were independent prognostic factors." (PMID 29567997, 2018). "The percentage of tumour tissues highly expressing NRBP1 was much smaller than that in matched normal tissues (P = 0.002)." (PMID 29567997, 2018).
tumor (continued). "The NRBP1 protein is downregulated in a wide variety of human tumours, and survival data analysis indicates that low expression correlates with poor prognosis." (PMID 26792023, 2016). "Subsequent work reported various roles for NRBP1 including interacting with Rac3 guanosine triphosphatase, controlling eye development, and operating as a negative regulator of gene transcription and tumor progression." (PMID 40668933, 2025). "Notably, TRIM24 knockdown markedly inducted apoptosis in GC cells through the modulation of NRBP1, a known context-specific tumor suppressor." (PMID 41430038, 2025). "Interestingly, NRBP1 (nuclear receptor binding protein 1) exerts distinct roles in different tumor contexts." (PMID 41430038, 2025). "Mechanistically, phosphorylation at the S42 residue may be a critical prerequisite for TRIM24 to recognize and degrade NRBP1, thereby modulating its tumor-suppressive function." (PMID 41430038, 2025). "Similarly, the suppression of NRBP1 led to a decrease in tumor growth, whereas its overexpression promoted tumor growth in a mouse model." (PMID 39149873, 2024). "Therefore, the specific mechanism of action of NRBP1 is still poorly understood in different tumor subtypes." (PMID 31413746, 2019). "To investigate whether NRBP1 affects tumor cell growth in vivo, we first constructed a lentiviral vector of shNRBP1 and its control shRNA (shCONT)." (PMID 31413746, 2019). "Moreover, we also found that NRBP1 knockdown significantly suppress tumor growth in xenograft mouse model." (PMID 31413746, 2019). "Thus, the results indicate that NRBP1 inhibits tumour growth by promoting the apoptosis of CRC cells." (PMID 29567997, 2018). "Interestingly, NRBP1 has also been shown to be involved in intestinal progenitor cell homeostasis with tumor suppressive function, suggesting its role is specific to the cellular context." (PMID 26572163, 2015). "To determine whether expression of mutant NRBP1 is required for tumor cell survival, we tested shRNA constructs in two HNSCC cells expressing all three forms of WT NRBP1 (OT9 cells) and mutant NRBP1 (NT8e cells)." (PMID 26572163, 2015). "Therefore, the tumor suppressive function of NRBP1 exhibits a certain degree of credibility." (PMID 41430038, 2025). "In addition, the biological activity of particular pathways downstream of NRBP1 may be context-dependent, as exemplified by Cdc42 exhibiting oncogenic or tumour suppressor functions depending on cancer type." (PMID 36693952, 2023). "Interestingly, NRBP1 is known to have different role in the tumor progression in different tumors." (PMID 31413746, 2019). "However, we did not observe a significant association between NRBP1 expression and age, gender, depth of infiltration, lymph node metastasis and distant metastasis, tumour differentiation, tumour histological type or location." (PMID 29567997, 2018). "However, in depth systematic sequencing of NRBP1 in a wide variety of tumor types may help indicate utility of NRBP1 inhibition in human cancer." (PMID 26572163, 2015). "U87‐sh‐control, U87‐sh‐NRBP1, U251‐Control, and U251‐pcDNA‐NRBP1 cells were injected subcutaneously into BABL/c nude mice, tumor volume was measured at 7‐day intervals." (PMID 39149873, 2024). "In addition, numerus recent works suggested regulatory roles of human NRBP1 and NRBP2 in tumor biology, as either tumor suppressor or activator." (PMID 40645931, 2025). "Negative or low expression of NRBP1 was detected in 50% (15/30) of tumour tissues compared to 13.3% (4/30) of paired normal tissues." (PMID 29567997, 2018). "In addition, NRBP1, which encodes multidomain putative adapter proteins, has an anti-tumor role against CRC tumorigenesis and progression, as an in vivo/in vitro study showed that the higher expression of NRBP1 inhibited CRC cell proliferation and anti-apoptosis and correlated with better prognosis." (PMID 34692549, 2021).
tumor (continued). "However, the role of NRBP1 in CRC has not been fully elucidated, and whether NRBP1 has a tumour suppressive function in CRC cells needs to be further validated." (PMID 29567997, 2018).
cancer (10 papers, 2015 to 2025). A tumor composed of atypical neoplastic, often pleomorphic cells that invade other tissues. "Of these, we find a heterozygous truncating mutation in Nuclear receptor binding protein, NRBP1 pseudokinase gene, identical to as reported in other cancers, is oncogenic when ectopically expressed in NIH-3 T3 cells." (PMID 26572163, 2015). "The pseudokinase NRBP1 has recently been described to have an important role in cancers, but the function and expression of NRBP1 in GBM is unidentified." (PMID 39149873, 2024). "To further clarify the expression level of NRBP1 mRNA in BCa and paracancerous tissues, we performed qRT-PCR on 20 pairs of cancer and adjacent tissues." (PMID 31413746, 2019). "Only recently has NRBP1 been proposed to have a role in cancer progression, but the role of NRBP1 is not fully understood because NRBP1 has been reported to have pro- or anti-cancer progression functions." (PMID 29567997, 2018). "Compared with adjacent normal tissues, the expression levels of NRBP1 mRNA were markedly downregulated in cancer tissues (16.3 ± 7.72 vs 10.6 ± 7.63, P = 0.008)." (PMID 29567997, 2018). "Compared with normal colorectal tissue, a low level of NRBP1 protein was detected in cancer tissue, and NRBP1 expression was low in the nine cell lines examined, especially in SW480 and HCT116 cells." (PMID 29567997, 2018). "In the past decade, NRBP1 has been found to play different roles in cancer development." (PMID 39149873, 2024). "The identification of P-Rex1 as a NRBP1 binding partner sheds new light on the oncogenic role of NRBP1, not only due to the well-established roles of Rac1/Cdc42 in human cancer, but also because P-Rex1 has recently emerged as an important oncogene in its own right." (PMID 36693952, 2023). "While MS has been previously used to identify NRBP1 binding partners, the context-specific roles of NRBP1 in cancer indicate that the NRBP1 interactome may vary according to cell type." (PMID 36693952, 2023). "However, in other cancers, NRBP1 appears to play an oncogenic role, although the detailed molecular mechanisms are lacking." (PMID 36693952, 2023). "NRBP1 has been revealed to exert different functions in different cancers." (PMID 34158077, 2021). "In PCa, high NRBP1 expression could be of prognostic value in PCa patients, and enhanced cancer cell proliferation." (PMID 34158077, 2021). "Since the research on NRBP1 and cancer has just begun, the exact regulatory mechanism is still largely unknown." (PMID 31413746, 2019). "The expression of NRBP1 protein tends to be lower in cancer tissues than in normal tissues." (PMID 29567997, 2018). "Previous studies have reported the prognostic value of NRBP1 expression in cancer." (PMID 29567997, 2018). "Interrogation of publicly-available data revealed that NRBP1 gene expression was significantly higher in the Basal Subgroup (predominantly TNBC) and HER2 cancers, compared to the other PAM50 subgroups." (PMID 36693952, 2023). "Furthermore, the DepMap database suggests that there is a notable codependence in cell viability between WNK1, NRBP1, and TSC22D2 in certain cancer cell lines, consistent with these components operating within a common pathway, and this was also highlighted in another recent study." (PMID 40668933, 2025). "Therefore, it is not surprising that NRBP1 has different mechanisms in different cancers." (PMID 31413746, 2019).
infection (3 papers, 2018 to 2024). The state of being infected such as from the introduction of a foreign agent such as serum, vaccine, antigenic substance or organism. "Moreover, numerous Ser/Thr kinases (STKs) were either increased (e.g., GRK2, ROCK2, ROCK1, PAK1) or decreased (e.g., BMP2K, TNIK, MYLK, and NRBP1) in expression in the patient samples, suggesting a widespread change in the kinome caused by pathogen infection." (PMID 38389037, 2024). "In the presence of Z-VAD-FMK, lenti-NRBP1 infection did not increase the percentage of Annexin V/PI positive cells in SW480 and HCT116 cells, indicating a critical role of caspases in the induction of apoptosis by NRBP1." (PMID 29567997, 2018).
NRBP1 also shares sentences with these, for which no sentence is quoted: nasopharyngeal carcinoma (2 papers); triple-negative breast carcinoma (2); Alcohol Use Disorders (1); autoimmune disease (1); depression (1); diabetes (1); dyslipidemia (1); glioblastoma (1); Hyperglycemia (1); idiopathic pulmonary fibrosis (1); osteoarthritis (1); pilocytic astrocytoma (1); prostate intraepithelial neoplasia (1); Takayasu arteritis (1).